IL10 (interleukin 10)
Diseases named in the same sentence as IL10 in open-access papers (continued):
Sharing a sentence is not in itself a finding about the gene and the disease.
viral infection (continued). "Interactions between a mild virus infection and exposure to cigarette smoke in an infant with the TA genotype might lead to high levels of IFN-γ, which could result in significant down regulation of IL-10 and dysregulation of pro-inflammatory responses to pyrogenic toxins." (PMID 25814991, 2015). "Moreover, IL-10 influences the IL-12/IFN-γ positive feedback loop during NK/DC crosstalk, but the consequences of these regulatory effects on the adaptive immune response during viral infections remain largely unknown." (PMID 22876184, 2012). "Unlike virus infection, vaccination with booster doses did not provoke equivalent IFN-γ and IL-10 expression memory T cells." (PMID 37383842, 2023). "Of note, CWDP was not capable of enhancing IL-10 levels or lung CD3+CD4+IL-10+ T cells, which was in line with their lower ability to reduce lung damage parameters during bacterial and viral infections when compared to viable D. pigrum 040417." (PMID 32414154, 2020). "The levels of the anti-inflammatory cytokine IL-10 and of the proinflammatory cytokines IL-5, TNF-α, IFN-γ, and GM-CSF increased after viral infection in both groups, regardless of 25(OH)D3 intake." (PMID 32635656, 2020). "Surprisingly, the knockout of the IL-10 gene in NK cells did not lead to an enhancement of T cell responses during chronic LCMV infection, casting uncertainty on the functional relevance of IL-10 derived from NK cells in the context of viral infections." (PMID 38022497, 2023). "As shown in our previous studies, together with IL-6, IL-10, and IFN-γ, the cytokine patterns are helpful in discriminating bacterial and virus infection, Gram-positive and negative bacterial infection, and invasive pulmonary aspergillosis and pneumocystis pneumonia." (PMID 35391735, 2022). "The increased levels of IL-10 and IFN-α2 may reflect the presence of a negative-feedback loop to control the inflammatory responses and virus infection." (PMID 33712622, 2021). "Thus, as opposed to localized defined foci, IL-10 expressing cells are dispersed throughout the spleen and essentially form a ‘blanket’ throughout the APC: T cell area during persistent virus infection." (PMID 26808628, 2016). "The cytokines IL-6, IL-10, IL-12, IL-17, TNF-α and IFN-γ were evaluated in the Cerebrospinal fluid (CSF) of patients with meningoencephalitis with and without viral infections as well as in control CSF samples using the cytometric bead array (CBA – BD biosciences)." (PMID 26286516, 2015). "Further analysis also showed that while the production of IL-6 and IL-10 are dependent on viral replication, production of TNF-α also occurs after exposure to UV-inactivated TCRV particles and is thus independent of productive virus infection." (PMID 21572983, 2011).
malaria (402 papers, 2005 to 2026). Malaria is a serious and sometimes fatal disease caused by a parasite that commonly infects a certain type of mosquito which feeds on humans. "A longitudinal prospective cohort study discovered that the − 1082A > G polymorphism is linked to decreased IL-10 levels and a reduced risk of clinical malaria in children." (PMID 40993672, 2025). "It has been observed that clinical or severe malaria is associated with increased levels of pro-inflammatory cytokines, including IL-1β, IL-6, IL-8, IL-10, IL-12, IL-13, IL-31, IL-33, and TNF-α." (PMID 39204168, 2024). "IL-10 plays an essential role in regulating inflammation during malaria and tissue damage caused by TNF." (PMID 39495782, 2024). "Increased levels of IL-1β and TNF, beyond TGF-b and IL-10, are associated with the major severity of malaria." (PMID 38774541, 2024). "In line with our results, previous studies have reported associations between malaria severity or death and proinflammatory cytokines and the anti-inflammatory cytokine IL-10." (PMID 36759905, 2023). "Collectively, our data suggest that malaria-specific, IL-10 and IFNγ producing Tr1 cells are more commonly found in primigravid women and are associated with an increased risk of malaria in pregnancy." (PMID 37634385, 2023). "Together, these results suggest that primigravid women have a malaria-specific CD4+ T cell response that is skewed towards IL-10 and is associated with a higher risk of malaria in pregnancy." (PMID 37634385, 2023). "In human malaria, hyperreactive malarial splenomegaly has been associated with significantly increased concentrations of IgM, anti-parasite IgG, IL-10, and IFN-γ." (PMID 36839438, 2023). "It is well-known that IL-10 plays a regulatory role in the development of pathogenesis associated with severe malaria, inducing an anti-inflammatory environment." (PMID 38256880, 2023). "TNF-α is the cytokine most implicated in the development of the clinical signs of malaria, while IL-10 and IL-6 are present at high levels in patients with symptomatic malaria." (PMID 35421083, 2022). "This clinical malaria control is also associated with increased IL-7, IL-10, IL-17, and IL-27 plasma levels as well as IgG and better parasite clearance." (PMID 36293524, 2022). "Asymptomatic malaria is associated with a strong polarization towards a regulatory immune response, presenting high circulating levels of IL-10." (PMID 35421083, 2022). "Studies in humans have suggested a role of IL-10 in regulating the pathogenic effects of TNF during malaria." (PMID 35464430, 2022). "For example, a study conducted in Western Kenyan children showed that higher ratios of plasma IL-10 to TNF levels were strongly linked to protection against severe malaria anaemia." (PMID 35464430, 2022). "In the present study, the SNPs of the two host genes involved in immune functions, i.e., TGFβ1 and IL10, and the one involved in malaria parasite binding (ICAM1) were significantly associated with P. falciparum parasitemia." (PMID 34698295, 2021). "Here, we show examples for Tr1 identification using IL-10 Foxp3 double reporter mice in the small intestine under steady-state conditions, and in a mouse model of malaria, a disease well known to be associated with Tr1 cells both in mouse and human." (PMID 34910301, 2021). "Applying this analysis to all participants with malaria, we observed that only MDP levels of IL-10 were directly associated with the number of previous malaria episodes." (PMID 34727121, 2021). "IL-10 is a pleiotropic cytokine that exhibits a variety of roles in regulating immunity and is regarded as critical for limiting malaria-associated immunopathology, severe disease, and mortality." (PMID 33529242, 2021). "IL-10 is a key immuno-regulator of immunity to infections and has been associated with various malaria-related phenotypes, such as uncomplicated malaria, severe malaria, severe malaria anaemia and high parasite density." (PMID 33593344, 2021).
malaria (continued). "Malat1−/− mice demonstrate enhanced macrophage activation and parasite clearance in the visceral leishmaniasis model, but more pronounced disease in experimental malaria, similarly to phenotypes observed in IL-10–deficient mice." (PMID 32321759, 2020). "Conversely, the IL-10 anti-inflammatory effect was associated with severe anemia and high parasitemia in experimental malaria." (PMID 32599864, 2020). "IL-10 plays a prominent role in the outcome of malaria disease in humans, and in the PcAS experimental model of malaria, IL-10 deficiency promotes severe disease manifested as more pronounced weight loss and mortality." (PMID 32321759, 2020). "Severe malaria has been associated with low serum levels of IL-12 and low IL-10 to TNF- α serum concentration ratios in a few studies of childhood malaria in holoendemic areas." (PMID 34557294, 2019). "Infection with Plasmodium falciparum, the main cause of malaria disease in Africa, induces inflammation which is normally regulated through induction of regulatory T cells and production of IL10 and TGF-β." (PMID 31618208, 2019). "Elevated levels of IL-10 with low TNF-α have been associated with mild malaria, whilst recovery from malaria (parasite clearance) has been associated with reduced levels of IL-10." (PMID 29970128, 2018). "The results of this prospective birth cohort study have shown that prenatal exposure to P. falciparum antigens is significantly associated with low IFN-γ and high IL-10 responses during clinical malaria episodes in the first two years of life." (PMID 30154871, 2018). "A low ratio of IL-10 to TNF in patients predicts more severe malaria, as do mutations in the IL-10 and TNF genes." (PMID 29866139, 2018). "Another study that compared the immune response of patients suffering complicated and uncomplicated malaria caused by P. vivax reported a higher IFN-γ/IL-10 rate in patients having complicated disease, as well as higher TNF-α level." (PMID 28243235, 2017). "This has also been observed in clinical studies where a low ratio of plasma TGF-β and IL-10 to TNF-α was associated with severe malaria anemia in young children in malaria endemic communities in Africa." (PMID 29034874, 2017). "IL-27 has been implicated in the regulation of IL-10 production by T cells during infection, such as in leishmaniasis and malaria." (PMID 28584007, 2017). "The risk of bacterial sepsis is increased in severe malaria, through immune mediated barrier dysfunction in the gut and bacterial translocation, as well as IL-10 mediated decreased control of bacteraemia." (PMID 28978319, 2017). "A unit increase in Log10 IL-10 was associated with a 1.42-fold (95% CI 1.03–1.96; p = 0.032) increase in odds of severe malaria." (PMID 27385484, 2016). "The objective of this study was to evaluate the frequency of -1031T>C, -308G>A and -238G>A TNFA, +874 A>T IFNG and -819C>T, and -592C>A IL10 gene polymorphisms and their association with malaria vivax and genomic ancestry." (PMID 27999453, 2016). "This was an interesting finding, since IL-10 is a well-known biomarker with regulatory role on inflammatory processes and for being directly associated to the protection in severe malaria." (PMID 27581163, 2016). "Similar models were constructed to examine significant associations between malaria disease severity and plasma IL-10 or arginase." (PMID 27385484, 2016). "CD4+ T cells producing other cytokines such IL-2, IL-10 and IL-4 alone or in combination with the studied cytokines have been shown to be associated with protection from malaria." (PMID 27165269, 2016). "Multivariate logistic regression analysis revealed a significant correlation of risk of severe malaria with both plasma IL-10 and soluble CD163 levels." (PMID 27385484, 2016). "This reported relative deficiency in IL-10 in fatal malaria cases possibly reflect an inadequate modulating response to an overwhelming pro-inflammatory cytokine production." (PMID 26953797, 2016).
malaria (continued). "The IL10A gene polymorphism at position −1082, have been associated with decreased production of IL-10 and clinical and severe malaria." (PMID 25627396, 2015). "Hepcidin was positively associated with IL-6 and IL-10 levels and with parasitaemia in subjects with mild malaria and with IFN-γ in subjects with severe malaria." (PMID 26466783, 2015). "Wild homozygous individuals with IL10A-592AA/-819TT presented IL-10 levels three times higher than individuals carrying variant allele C, indicating an association between the AA/TT genotypes with clinical malaria risk." (PMID 25627396, 2015). "In malaria, polymorphisms in the promoter region (IL-10A-1082A/G, −819 T/C and -592A/C) were associated with reduced IL-10 plasma levels and with the development of acute anaemia in Kenyan children with P. falciparum malaria in holoendemic areas." (PMID 25627396, 2015). "Hepcidin was positively associated with IL-6, IL-10, and parasitaemia in the mild malaria group and with IFN-γ in the severe malaria group, which suggests a possible role of immunological regulation in the expression of this hormone." (PMID 26466783, 2015). "It is known that the expression of anti-inflammatory cytokines such as IL4 and IL10 is critical in the control of anaemia and severe malaria and the expression of these cytokines is associated with biochemical patterns of iron deficiency in infected children." (PMID 25890318, 2015). "In association, decreased malaria-specific IFN-γ secretion by individuals with patent infections was shown to be IL-10 dependent." (PMID 25889652, 2015). "IL-10 is an anti-inflammatory cytokine with a controversial role in malaria; high concentrations of IL-10 are associated with both severe disease and protection." (PMID 25889717, 2015). "IL-10 has consistently been shown to be associated with favourable outcome in malaria and other infections and our data now link this protective anti-inflammatory response to hepcidin secretion." (PMID 24520384, 2014). "Different from IL-6 and CXCL-8, evidences suggest that exacerbated levels of IFN-γ are directly correlated with the severity of the malaria caused by P. vivax and the more severe the symptoms are the lower levels of IL-10 are produced." (PMID 24741587, 2014). "This IL-10 dependent defect in macrophage function is likely to act together with additional immune defects caused by malaria." (PMID 24787713, 2014). "Altogether, it is shown that both inflammatory and anti-inflammatory cytokines are produced during malaria caused by P. vivax and the levels of IL-6 and IL-10 are dependent on the parasite load." (PMID 24741587, 2014). "Mendonca and coworkers recently showed correlation between the levels of IL-10 and parasite burden in patients experiencing severe malaria caused by P. vivax." (PMID 24741587, 2014). "IL-10, important to counterbalance inflammation and associated with protection from inflammatory-mediated severe malaria in both humans and experimental models, was originally considered be produced by CD4+ Th2 cells during infection." (PMID 25628621, 2014). "Regulatory cytokines, such as IL-10, are required to reduce the risk of severe disease or more tissue injury in malaria." (PMID 25128199, 2014). "Analysis of biomarker network suggests that IL-10 and IL-6 are a robust axis in malaria patients and that this interaction seems to be associated with the parasite load." (PMID 24741587, 2014). "Our findings establish a clear interaction between an inflammatory cytokine, IL-6, and an anti-inflammatory cytokine, IL-10, and correlation of the former with parasite load during malaria caused by P. vivax." (PMID 24741587, 2014). "The aim of this study was to investigate the annexin-A1 expression in CD4+, CD8+ T cells, regulatory T cells (Treg) and cytokine IL-10 quantification in plasma from patients with malaria caused by P. vivax." (PMID 24359168, 2013).
malaria (continued). "A ratio of IL-10:TNF of less than 1 correlated with severe malaria whereas a ratio of more than 1 was associated with uncomplicated malaria." (PMID 23874969, 2013). "IL-10 is an immunoregulatory cytokines and has been associated with the amelioration of the pathology and death in murine malaria." (PMID 23323093, 2012). "The expressions of NF-κB p65 in the PBMCs from malaria patients and the plasma levels of IL-10 and TNF were measured by using enzyme-linked immunosorbent assay (ELISA)." (PMID 22682094, 2012). "Plasma concentrations of IL-10, IL-12 and IL-13 were associated with current infection or prior malaria episodes." (PMID 22280502, 2012). "When analysed at the level of individual SNPs, an association was discovered for those individuals displaying IL10 - 1082 with a reduced risk for malaria symptoms." (PMID 22615793, 2012). "IL-10 limits the inflammatory responses provoked by many stimuli including normal homeostasis and IL-10 has been variously implicated in malaria pathophysiology." (PMID 21687657, 2011). "This study also establishes an association between HLA polymorphisms and IL-10 production in severe malaria." (PMID 21447146, 2011). "For malaria, these effects were mainly short-term, observed only in the presence of current infection; however, decreased IL-5 cCFP and increased IL-10 TT responses were associated with both current and previous malaria." (PMID 21040693, 2010). "Functional studies on the association of G-CSF and IL-10 with asymptomatic malaria are much needed to reveal their contribution to the spread and severity of malaria." (PMID 20706538, 2010). "Further, our results from the T-cell activation and cytokine secretory profiles led us to propose that a malaria-induced shift from the Th1 IFN-γ response to a regulatory T cell–based IL-10 response is one possible mechanism for the loss of control of EBV in eBL etiology." (PMID 41285032, 2025). "However, in field studies, declining or dysregulated IL-10 have been implicated in the development of severe anemia during infectious diseases such as malaria." (PMID 41306959, 2025). "While IL-10 is an anti-inflammatory cytokine, its dysregulation, including insufficient regulation of pro-inflammatory responses, may be associated with severe malaria." (PMID 38694310, 2024). "In contrast, IL-10 was proposed to influence the susceptibility to coinfections in asymptomatic malaria parasitaemia, which might result from a brittle equilibrium of inflammatory agents slightly in favour of resolution." (PMID 37658365, 2023). "In a previous work conducted in Gabon, we showed that IL-10 may be a better indicator of asymptomatic infection, as significantly higher levels of IL-10 were associated with asymptomatic forms of malaria in urban, semi-urban and rural areas." (PMID 36787308, 2023). "IL-10 levels play an essential role in reducing the inflammatory response during malaria infection, and increased levels of IL-10 were identified in the plasma of patients with malaria-associated splenomegaly." (PMID 37628675, 2023). "In our study IL-10 was associated with malaria severity as in several studies." (PMID 37365194, 2023). "The IL-12 levels were reported to be lower in patients with severe malaria, particularly in those with severe malarial anemia, because the ingestion of malarial pigments by monocytes promoted the overproduction of IL-10, TNF-α, or TGF-β, and caused a lower production of IL-12." (PMID 35954703, 2022). "Indeed, dysregulation of IL-10 is frequently associated with enhanced immunopathology, as many of the severe complications observed in a wide range of infections (including malaria) result from excessive immune activation." (PMID 35768411, 2022). "Indeed, high levels of IL-10 have already been linked to increased disease severity in humans, including for example cerebral malaria and lung pathology called malaria-associated acute respiratory distress syndrome (MA-ARDS)." (PMID 35464430, 2022).